Y_RNA (Y RNA )
Gene: Miscellaneous RNA gene on chromosome 10 (101,952,605 to 101,952,704, reverse strand). Ensembl gene ENSG00000222430.
Homologues: Orthologues: chimpanzee Y_RNA (98% identical). Paralogues in human: RNY1 (83% identical), Y_RNA (82% identical), Y_RNA (81% identical), Y_RNA (80% identical), Y_RNA (79% identical), Y_RNA (78% identical), Y_RNA (77% identical), RNY1P11 (76% identical), RNY1P7 (76% identical), Y_RNA (76% identical), Y_RNA (75% identical), RNY1P5 (74% identical), and 95 more.